MOG (myelin oligodendrocyte glycoprotein)
Diseases named in the same sentence as MOG in open-access papers (continued):
Sharing a sentence is not in itself a finding about the gene and the disease.
multiple sclerosis (continued). "Myelin oligodendrocyte glycoprotein antibody-associated disease (MOGAD) is an inflammatory demyelinating disease that is distinct from multiple sclerosis." (PMID 36341089, 2022). "One study has compared the infiltrating cell types in patients with TDL (acute phase, biopsies, n = 4), in Multiple Sclerosis patients (chronic phase, autopsy, n = 11), in MOG-antibody associated disease (n = 11, biopsies) and ADEM cases (n = 5, biopsies)." (PMID 35418930, 2022). "The hallmark of multiple sclerosis (MS), an autoimmune neuroinflammatory disease, is the presence of autoantibodies against the myelin oligodendrocyte glycoprotein (MOG)." (PMID 34063669, 2021). "In summary, more human multiple sclerosis risk genes were differentially expressed in OSE than was observed for MOG EAE, especially in TH1 cells." (PMID 33072080, 2020). "Only until she was tested positive for MOG-IgG that her diagnosis was revised from multiple sclerosis to MOG-associated disease (MOGAD)." (PMID 33281696, 2020). "With improvements in molecular testing techniques, some of these conditions are now known to represent forms of neuromyelitis optica spectrum disorder, MOG antibody associated disease, and multiple sclerosis." (PMID 31109018, 2019). "The clinical, radiological, and pathological findings of MOG-IgG-associated disorders were distinct from those with multiple sclerosis or NMOSD-AQP-IgG." (PMID 30382857, 2018). "Antibodies with specificity for myelin oligodendrocyte glycoprotein (MOG) are implicated in multiple sclerosis and related diseases." (PMID 28646890, 2017). "Myelin oligodendrocyte glycoprotein antibody (MOG Ab) associated demyelination represents a subgroup of autoimmune demyelination that is separate from multiple sclerosis and aquaporin 4 IgG-positive NMO, and can have a relapsing course." (PMID 26919719, 2016). "The displayed myelin oligodendrocyte glycoprotein (MOG) was used as an example depicting diagnostic analysis of the autoimmune disease multiple sclerosis (MS)." (PMID 17204164, 2007). "Myelin oligodendrocyte glycoprotein antibody-associated disease (MOGAD) is a demyelinating disorder of the central nervous system (CNS) distinct from multiple sclerosis (MS) and aquaporin 4 (AQP4) immunoglobulin G (IgG) antibody-associated neuromyelitis optica spectrum disorder (NMOSD)." (PMID 38783085, 2024). "However, MOG-AD usually shows more edematous and extensive inflammatory lesions that tend to spare the optic chiasm and tracts when compared to multiple sclerosis-associated or aquaporin-4-positive (AQP4) NMOSD-associated ON." (PMID 38975430, 2024). "Additionally, CBD treatment decreased inflammation and axonal loss in multiple sclerosis models engineered with myelin oligodendrocyte glycoprotein (MOG) to imitate EAE." (PMID 38399295, 2024). "Therefore, autoantibodies against MOG have long been considered a potential cause of human inflammatory demyelinating diseases, particularly multiple sclerosis (MS)." (PMID 37545724, 2023). "Among patients fulfilling 2017 McDonald criteria for multiple sclerosis, MOG-IgA was associated with less frequent CSF-specific oligoclonal bands (4/9 [44%] vs 325/351 [93%], respectively; P < .001) vs patients with multiple sclerosis who were MOG-IgG/IgA seronegative." (PMID 37548987, 2023). "In the particular case of multiple sclerosis (MS), there are strong indications that the loss of tolerance is directed toward various myelin proteins, including myelin oligodendrocyte glycoprotein (MOG), myelin basic protein (MBP), and proteolipid protein (PLP)." (PMID 33679769, 2021). "Here we report three cases of anti-myelin oligodendrocyte glycoprotein (MOG) antibody-associated disease (MOGAD) mimicking multiple sclerosis in which seropositivity for anti-MOG antibodies occurred during disease-modifying drug dimethyl fumarate (DMF) treatment." (PMID 33659007, 2021).
multiple sclerosis (continued). "Recently, in addition to AQP4-IgG associated NMOSD, the identification of myelin oligodendrocyte glycoprotein (MOG) antibodies has broadened the spectrum of antibody-associated CNS demyelinating-inflammatory diseases that are distinct from classical multiple sclerosis." (PMID 34737756, 2021). "This cohort study examines the clinical and magnetic resonance imaging (MRI) features and outcomes associated with spinal cord involvement in pediatric myelin oligodendrocyte glycoprotein antibody–associated disease, multiple sclerosis, and seronegative monophasic myelitis." (PMID 34643718, 2021). "The German Neurological Society’s (Deutsche Gesellschaft für Neurologie, DGN) Guideline on Diagnosis and Treatment of Multiple Sclerosis, Neuromyelitis Optica Spectrum Diseases and MOG-IgG-Associated Disorders has recently been revised and published in German." (PMID 34362474, 2021). "Unilateral or bilateral optic neuritis presenting as sudden visual loss may be associated with antibodies to AQP4 (NMO spectrum disease) or MOG (MOG antibody- associated disease) or multiple sclerosis (usually unilateral)." (PMID 33935958, 2021). "EAE, the classical rodent model for multiple sclerosis, could better reflect the neuropathology of human MOG Ab-associated disorders, however consideration of the major human epitope of MOG Ab should be prioritised in future in vivo studies." (PMID 31481127, 2019). "This may suggest that the consumption of milk and milk products, especially the dietary BTN, could modulate the pathogenic autoimmune response to MOG in multiple sclerosis." (PMID 29401697, 2018). "All the MOG variants including full-length (MOG 25.1/25.6, MOG 20.5, MOG 20.2, MOG 22.2/22.7, MOG 16.3 alpha 4 and MOG 16.3 beta 4) were detectable in brain tissue (normal appearing white matter) samples from individuals with multiple sclerosis." (PMID 17573820, 2007). "The detection of myelin oligodendrocyte glycoprotein (MOG) antibodies in cases of optic neuritis (ON) has recently led to the differentiation of MOG immunoglobulin G associated optic neuritis (MOG-ON) from the more common idiopathic or multiple sclerosis (MS) associated optic neuritis (MS-ON)." (PMID 32785840, 2021). "Indeed, recent years have witnessed rapid expansion in the clinical spectrum of disorders associated with MOG antibodies (MOG Ab), and their detection is now implemented to diagnose patients with CNS demyelinating disorders phenotypically distinct from multiple sclerosis." (PMID 31481127, 2019). "This led us to select a panel of TCRL Abs targeting the immunodominant autoantigenic epitope MOG35-55 derived from myelin oligodendrocyte glycoprotein (MOG) presented on HLA-DR2, which is associated with multiple sclerosis (MS)." (PMID 39496501, 2025). "A subset of patients with antibodies against MOG expresses a clinical phenotype distinct from multiple sclerosis (MS)." (PMID 40564099, 2025). "The six patients in the previous report included three with anti-MOG antibody-positive optic neuritis, two with multiple sclerosis, and one with idiopathic optic neuritis." (PMID 40265085, 2025). "Myelin oligodendrocyte glycoprotein antibody-associated disorder (MOGAD) is a distinct inflammatory demyelinating disorder of the central nervous system (CNS), separate from multiple sclerosis (MS) and neuromyelitis optica spectrum disorders (NMOSD)." (PMID 40547008, 2025). "With advancements in antibody detection methods, specific MOG-IgG has been detected in non-multiple sclerosis (MS) patients with conditions such as optic neuritis and acute disseminated encephalomyelitis." (PMID 40406135, 2025). "The recently proposed 2023 Banwell diagnostic criteria suggest that the presence of MOG antibodies, and clinical and MRI evidence are required for a confirmatory MOGAD diagnosis, once potential alternatives such as multiple sclerosis have been excluded." (PMID 40696221, 2025).
multiple sclerosis (continued). "NMOSD, multiple sclerosis (MS), and myelin oligodendrocyte glycoprotein antibody disease (MOGAD) are CNS demyelinating diseases." (PMID 40568579, 2025). "For instance, in a murine model of multiple sclerosis, engineered platelets expressing myelin oligodendrocyte glycoprotein (MOG) successfully modulated autoimmune responses and prevented disease onset." (PMID 40943069, 2025). "We conducted a matched cohort study using prospectively collected educational data in multiple sclerosis (MS) and myelin oligodendrocyte glycoprotein antibody disease (MOGAD) patients (n = 60) and controls (pooled n = 449,553)." (PMID 39359055, 2024). "We acknowledge the controversy of diagnosing a MOG-positive case as atypical multiple sclerosis The primary rationale for inclusion is the subsequent clinical course and radiological progression was more in line with MS than MOG." (PMID 38861035, 2024). "Myelin oligodendrocyte glycoprotein antibody (anti-MOG) is the defining biomarker of MOG antibody-associated disease (MOGAD), an inflammatory demyelinating disease that is distinct from multiple sclerosis (MS)." (PMID 38550339, 2024). "MOG is a clinically relevant protein for neurodegeneration because of anti-MOG-related neurologic disease, which partially overlaps with multiple sclerosis." (PMID 39598329, 2024). "The hemorrhagic brainstem lesions were inconsistent with a typical presentation of multiple sclerosis (MS), myelin oligodendrocyte glycoprotein (MOG), or NMO." (PMID 39687819, 2024). "Multiple sclerosis (MS), aquaporin 4-antibody neuromyelitis optica spectrum disorder (AQP4 + NMOSD) and myelin oligodendrocyte glycoprotein antibody–associated disease (MOGAD) are the most defined forms." (PMID 38646958, 2024). "False positive diagnoses can arise from MOG-IgG seropositivity at lower titers in other demyelinating diseases, such as multiple sclerosis (MS)." (PMID 38804311, 2024). "Percutaneous administration of BTN in patients with multiple sclerosis induced the development of MOG-specific tolerance for MOG-specific immunotherapy." (PMID 39742102, 2024). "Both anti-myelin oligodendrocyte glycoprotein with anti-major basic protein belongs to early and late multiple sclerosis (MS) predictors." (PMID 37046492, 2023). "The injection of MOG peptide is a model of autoimmune encephalomyelitis used to study multiple sclerosis." (PMID 38069274, 2023). "Research in recent decades has proven that autoimmunity against MOG exists, mimicking the clinical course of multiple sclerosis and neuromyelitis optica (NMO)." (PMID 38131803, 2023). "Three MOG positive cases had a prototypical multiple sclerosis diagnosis (RRMS n = 2, titers 1:20 and 1:40; PPMS n = 1; 1:100)." (PMID 35795797, 2022). "First evidence shows a direct antibody-antigen interaction in multiple sclerosis in preclinical autoimmune encephalomyelitis models against MOG." (PMID 36289819, 2022). "To this end, we employed EAE as a well-established autoimmune disease model of multiple sclerosis in which the immunization of mice with MOG peptide plus adjuvants results in the DC-mediated activation of autoreactive Th1/Th17 responses." (PMID 35883631, 2022). "The clinical relevance of MOG-IgG positivity in patients with atypical phenotypes for MOG-AD and/or more likely alternative diagnoses, such as multiple sclerosis, is thus an area that would benefit from future exploration." (PMID 35795797, 2022). "An example is the development of immunoregulators (epitope peptides of MBP and MOG) for Multiple Sclerosis, which serve as platforms for the design, synthesis, and development of MS therapeutics and vaccines." (PMID 35447967, 2022). "Myelin oligodendrocyte glycoprotein (MOG)-induced experimental autoimmune encephalitis (EAE) is a mouse model of multiple sclerosis shown to benefit from MSC therapy." (PMID 34764248, 2021).
multiple sclerosis (continued). "In the central nervous system (CNS), myelin basic protein (MBP) or myelin oligodendrocyte glycoprotein (MOG) can be targeted in multiple sclerosis (MS)." (PMID 34552599, 2021). "EAE is designed to model the autoimmune response to myelin oligodendrocyte glycoprotein (MOG) observed in multiple sclerosis." (PMID 34858434, 2021). "In 24/37, red flags were present, predominantly MOG‐IgG at assay cutoff and/or MRI lesions suggestive of multiple sclerosis (MS)." (PMID 33047894, 2021). "What features distinguish spinal cord involvement in children with myelin oligodendrocyte glycoprotein antibody–associated disease (MOGAD), multiple sclerosis (MS), and seronegative monophasic myelitis?" (PMID 34643718, 2021). "MOG-reactive Th17 cells are known to induce autoimmune neuroinflammation, and IL-17A has been proposed as a promising target for the treatment of multiple sclerosis (MS)." (PMID 31936879, 2020). "To this end, we compared gene expression in OSE and MOG EAE models and analyzed the relationship of both models to human multiple sclerosis risk genes and T helper cell biology." (PMID 33072080, 2020). "Mannan (polysaccharide) conjugated with a myelin oligodendrocyte glycoprotein (MOG) peptide, namely (KG)5MOG35–55, represents a potent and promising new approach for the immunotherapy of Multiple Sclerosis (MS)." (PMID 33066323, 2020). "They analyzed serum cfDNA and showed a difference in the methylation status in the MOG gene in oligodendrocytes from multiple sclerosis patients and in a mouse model of the disease." (PMID 32813850, 2020). "The peptide segment corresponding to residues 35–55 (MEVGWYRSPFSRVVHLYRNGK) of myelin oligodendrocyte glycoprotein (MOG) was considered as a potential peptide vaccine for multiple sclerosis." (PMID 32945974, 2020). "First, we analysed a panel of 32cytokines/chemokines in a discovery group (nine aquaporin-4-antibodyseropositive, nine myelin oligodendrocyte glycoprotein-antibodyseropositive, eight encephalitis, 10 multiple sclerosis)." (PMID 31205739, 2019). "Most of thesecytokines/chemokines were up-regulated in autoantibodies against aquaporin-4or autoantibodies against myelin-oligodendrocyte-glycoprotein positivepatients compared to multiple sclerosis." (PMID 31205739, 2019). "We treated a myelin oligodendrocyte glycoprotein (MOG) antibody disease patient who had been prescribed dimethyl fumarate because she was thought to have been suffering from multiple sclerosis (MS)." (PMID 31824807, 2019). "In a subgroup of AQP4 antibody (AQP4-IgG) seronegative NMOSD patients as well as in patients with recurrent optic neuritis and a few patients with multiple sclerosis (MS) an antibody against myelin oligodendrocyte glycoprotein (MOG-IgG) can be detected." (PMID 31258505, 2019). "It has been reported that anti-MOG autoantibodies were detected in the brain of multiple sclerosis (MS) and neuromyelitis optica (NMO) patients." (PMID 30978197, 2019). "A study on five MOG Ab seropositive adult patients with multiple sclerosis demonstrated the recognition of varying epitopes between all patients." (PMID 31481127, 2019). "In order to search for a potential CRION marker we have measured brain atrophy in a cohort of patients, stratified by phenotypes: CRION, RION, multiple sclerosis with a history of optic neuritis (MS-ON), and MOG-Abs status." (PMID 31736862, 2019). "MOG antibody disease spontaneously separated from multiple sclerosis, but overlapped with AQP4 antibody disease." (PMID 31212763, 2019). "In an EAE mouse model of multiple sclerosis (MS), it was found that following immunization with myelin oligodendrocyte glycoprotein (MOG), systemic treatment with DNA nanoparticles (DNPs) or cyclic diguanylate monophosphate (c-diGMP) induced STING signaling." (PMID 31781097, 2019).
multiple sclerosis (continued). "In an animal model of multiple sclerosis (MS), the Myelin Oligodendrocyte Glycoprotein (MOG)-induced Experimental Allergic Encephalomyelitis (EAE) model, CD200−/− mice showed a more rapid onset of disease as compared to C57BL/6 WT mice." (PMID 29533975, 2018). "For example, multiple sclerosis has been treated by targeting the autoantigen myelin oligodendrocyte glycoprotein (MOG) with immunotoxins containing ETA' or DTA, resulting in the specific depletion of the autoreactive cell population in mouse models." (PMID 28704435, 2017). "In a murine model of multiple sclerosis, experimental autoimmune encephalopathy, 14-dehydroergosterol suppressed the clinical score and inflammatory responses of myeloid DCs and T cells to myelin oligodendrocyte glycoprotein." (PMID 29066789, 2017). "Relapsing MOG Ab demyelination syndromes are considered distinct from multiple sclerosis (MS) based on clinical and neuroimaging features, and MOG antibody seropositivity is associated with a non-MS course at 1-year follow-up." (PMID 26919719, 2016). "Of further importance, fusion of CTB with myelin oligodendrocyte glycoprotein (MOG) provided protection against the development of multiple sclerosis." (PMID 25714914, 2015). "Myelin oligodendrocyte glycoprotein (MOG) is a key CNS-specific autoantigen for primary demyelination in multiple sclerosis." (PMID 26378585, 2015). "The idea of specifically generating MOG-reactive Tregs is also particularly attractive for the therapy of Multiple Sclerosis where, based on our data in the EAE mouse model, we believe that Tregitope peptides induce antigen-specific adaptive tolerance." (PMID 24454476, 2013). "Autoantibodies directed against myelin antigens have been a long-standing focus of interest in multiple sclerosis (MS) research, especially those binding to myelin oligodendrocyte glycoprotein (MOG)." (PMID 22093619, 2011). "This cross-sectional cohort study explores the potential role of antibodies to myelin oligodendrocyte glycoprotein (MOG), a putative autoantigen in multiple sclerosis, in the pathogenesis of HAND." (PMID 21083890, 2010). "Recurrent episodes of optic neuritis indicate a possible cause for the development of more generalized diseases, including multiple sclerosis, neuromyelitis optical spectrum disorder (NMOSD), and myelin-oligodendrocyte glycoprotein (MOG)-IgG-associated disease." (PMID 40002778, 2025). "Smoking and vascular risk factors (VRFs) are reported to have adverse effects in multiple sclerosis but data are limited in aquaporin-4 antibody-positive neuromyelitis optica spectrum disorder (AQP4-NMOSD) and myelin oligodendrocyte glycoprotein antibody disease (MOGAD)." (PMID 40088045, 2025). "Moreover, NMOSD is often confused with multiple sclerosis (MS) and myelin oligodendrocyte glycoprotein antibody disease (MOGAD)." (PMID 40568579, 2025). "Optic neuritis (ON) is a common feature of inflammatory demyelinating diseases (IDDs) such as multiple sclerosis (MS), aquaporin 4-antibody neuromyelitis optica spectrum disorder (AQP4 + NMOSD) and myelin oligodendrocyte glycoprotein antibody–associated disease (MOGAD)." (PMID 38646958, 2024). "Children diagnosed with multiple sclerosis had greater structural compromise relative to children with myelin oligodendrocyte glycoprotein-associated disorders; there were no group differences in neural synchrony." (PMID 39534724, 2024). "Myelin oligodendrocyte glycoprotein antibody associated disease (MOGAD) defines a subgroup of patients with central nervous system (CNS) inflammation with MOG-IgG that is distinct from multiple sclerosis (MS) and aquaporin-4 (AQP4)-IgG positive neuromyelitis optic spectrum disorder (NMOSD)." (PMID 39148657, 2024). "This cross-sectional study examines whether proposed myelin oligodendrocyte glycoprotein antibody–associated disease (MOGAD) diagnostic criteria can exclude other diseases, such as multiple sclerosis, and rely on results of cell-based assays." (PMID 37814961, 2023).